NQO1 (NAD(P)H quinone dehydrogenase 1)
Diseases named in the same sentence as NQO1 in open-access papers (continued):
Sharing a sentence is not in itself a finding about the gene and the disease.
tumor (continued). "Pan-cytokeratin-positive tumor cells in the first row showed over 9000 signal intensity of the FITC channel, which was used to visualize NQO1, while the tumor cells in the second row had less than 1000 signal intensity." (PMID 36359002, 2022). "KP372-1 + PARPi treatment results in robust, NQO1-dependent, tumor-selective induction of DNA DSBs, autophagy and apoptosis both in vitro and in vivo." (PMID 36203459, 2022). "This AKT hyperactivation further inhibits FOXO3a/GADD45α pathway resulting in even greater DNA DSBs induction, and cells undergo tumor-selective and NQO1-dependent autophagy and apoptosis." (PMID 36203459, 2022). "The theragnostic potency of NQO1-responsive polymeric vesicles was also evaluated with in vivo fluorogenic imaging of tumor-bearing mice." (PMID 35269324, 2022). "Studies comparing NQO1 expression under hypoxic and normoxic conditions in different tumor lines provide contradictory information." (PMID 35681666, 2022). "The results revealed that when the prognostic indicator was OS, high grade residual tumor, metastasis, positive margin status, high expression of HELLS and STMN1, low expression of EPAS1, CXCL2, NQO1, IL6 were associated with poor prognosis." (PMID 34982796, 2022). "Based on Spearman and Kendall rank correlation test, the folds change of pirin expression in tumour vs. the corresponding normal tissues correlated with the fold change of NQO1 expression (p = 0.001271 and p = 0.0008092)." (PMID 35204145, 2022). "NQO1 is the main enzyme target protein of Nrf2, regulating oxidative stress and ferroptosis in tumor cells through the Nrf2/HO-1 signaling pathway." (PMID 35883650, 2022). "It is well understood that the reduction of Lap to its cytotoxic hydroquinone form is mediated by the endogenous NQO1 enzyme, of which the expression levels are abnormally upregulated in tumor cells but remain normal in immune cells." (PMID 36167857, 2022). "Out of 39 randomly-selected (pre)neoplastic tumor lesions with middle/high expression of NQO1 that were analyzed for p62 expression on consecutive sections, 64% consisted mostly of hepatocytes exhibiting high numbers of p62 aggregates." (PMID 35626041, 2022). "The results of cytotoxicity showed increase in toxicity on NQO1+ cells over NQO1- cells anticipating β-Lapachone micelles as a promising nanocarrier against NQO1-overexpressing tumor cells." (PMID 35903701, 2022). "NQO1 acts as both a tumor suppressor and tumor promoter; thus, the inhibition of NQO1 results in less tumor burden." (PMID 34833955, 2021). "We then compared the methylation levels of Nqo-1 and Aldh1a3 in tumor infiltrated immune cells including TAMs, CD4+T cells, and CD8+T cells to BMDMs from the same KPC mouse." (PMID 34711804, 2021). "Direct silencing of NQO1 expression reveals an important role for NQO1 in protecting tumor cells from phenformin-generated oxidative stress." (PMID 34083537, 2021). "Since NQO1 is expressed at higher levels in many human solid tumors compared to normal tissue, this allows for the selective activation of these prodrugs in tumor cells." (PMID 34437536, 2021). "It is possible that a small number of circulating PDA tumor cells have infiltrated into the bone marrow and induced a modest elevation of the Nqo-1 and Aldh1a3 methylation in BMDMs in KPC mice." (PMID 34711804, 2021). "NQO1 deficiency promotes estrogen-dependent tumor formation, and shikonin inhibits estrogen-dependent tumor growth in an NQO1-dependent manner in MCF-7 xenografts." (PMID 33435147, 2021). "In TNF induced NF-κB activation, quinone oxidoreductase 1 (NQO1) plays a pivotal role in activation of NF-κB signaling, and inhibition of NQO1 activity hampers the proliferation, survival, invasion, and metastasis of tumor cells." (PMID 33526051, 2021). "Conversely, there was a statistically significant decrease in NQO1 mRNA expression in tumor tissue at 72 h after SDT (day 11) compared to the control animal group (p ≤ 0.001)." (PMID 34681196, 2021).
tumor (continued). "We chose Aldh1a3 and Nqo-1, whose methylation sequences were the best defined, to be examined for tumor-induced methylation in macrophages by MSP." (PMID 34711804, 2021). "Novel nanoparticles targeting NQO1 are able to act as better PS carriers, can rearrange the PS to a higher absorption peak, and work better in a hypoxic tumor microenvironment." (PMID 34947831, 2021). "In particular, NQO1 exerts many biological activities, including antioxidant activities, anti-inflammatory effects, and interactions with tumor suppressors." (PMID 34947831, 2021). "In this study, we show that dunnione (a strong substrate of NQO1) attenuates the prothrombotic state and lung thrombosis in tumor-bearing mice by inhibiting the expression of tissue factor and formation of neutrophil extracellular traps (NETs)." (PMID 34769515, 2021). "β-lapachone (β-lap, in clinical form, ARQ761), a tumor-selective drug, is a NAD(P)H: quinone oxidoreductase 1 (NQO1) bioactivatable drug." (PMID 34789190, 2021). "Blocking either GARP or integrin would suppress tumor-induced DNA methylation in Nqo-1 gene and the reprogramming of M1-like macrophages." (PMID 34711804, 2021). "Mechanistically, LPC downregulates the Gal-3/Gal-3BP/IL6 axis between NB cells and iBMSC in an NQO1-dependent manner, thereby inhibiting the tumor-promoting effect of iBMSC-derived IL6 on NB cells." (PMID 34790130, 2021). "Both in vitro and in vivo studies demonstrate the excellent antitumor activity of ZIF67/Ola/Lapa in NQO1 overexpressed MDA-MB-231 tumor cells." (PMID 34481495, 2021). "NAD(P)H quinone oxidoreductase 1 (Nqo1), one of the most critical quinone reductases, has been well-documented to play crucial roles in antioxidant protection and tumor-killing." (PMID 34566651, 2021). "Consistently, our western blotting analysis revealed that NQO1 protein levels were obviously elevated in 43.8% (28/64) of HCC tumor tissues, while catalase levels were repressed significantly in most HCC tumor tissues." (PMID 34676172, 2021). "TUNEL assay indicated extensive apoptosis in tumor tissues, suggesting that depletion of either NQO1 or GSTP1 triggers apoptosis, with the combined knockdown producing more extensive apoptotic cell death than the other groups." (PMID 33087132, 2020). "Recently, KP372-1 was identified as a novel NQO1-bioactivatable compound that generates reactive oxygen species (ROS) and exhibits ~ 10 times greater anti-tumor activity than β-lap17." (PMID 33214574, 2020). "To study clinical correlation, we first analyzed Nrf2, PRDX5 and NQO1 mRNA expression in both tumor tissues and the adjacent normal tissues, and the results showed upregulated these mRNAs in tumors." (PMID 31899687, 2020). "Lapa can produce sufficient O2-• under the catalysis futile redox cycles of NAD(P)H:quinone oxidoreductase-1 (NQO1) enzyme, which is overexpressed 100-fold in tumor cells than normal cells 38-40." (PMID 32483451, 2020). "Knockdown of either NQO1 or GSTP1 separately significantly decreased tumor volumes and weight, and combined knockdown resulted a much greater effect." (PMID 33087132, 2020). "NQO1 is also highly expressed in other tumor cells, such as breast cancer, lung cancer, prostate cancer, gastric cancer, colon cancer, pancreatic cancer, head and neck cancer, and cholangiocarcinoma." (PMID 33005608, 2020). "After the NQO1-responsive nanovesicles entered into the tumor cells, the NQO1 in the tumor cells triggered the self-immolative cleavage of the quinone trimethyl lock, the release of the PS, and the simultaneous NIR emission and PDT activation." (PMID 33134254, 2020). "Specifically, our results demonstrate that the loss of KEAP1 in human cells leads to a significant increase in NQO1 expression, which is known to facilitate tumor growth through HIF-1 binding." (PMID 32424161, 2020).
tumor (continued). "The released Lapa generated a large amount of ROS, consumed ATP, and downregulated P-glycoprotein (P-gp) production through the activity of NQO1, an enzyme that is specifically overexpressed in tumor cells." (PMID 32706272, 2020). "This combination therapeutic strategy presents a unique tumor-selective and minimally toxic approach for targeting solid tumors that overexpress NQO1." (PMID 32974194, 2020). "To understand the link between NQO1 and tumor cell plasticity, we analyzed publicly available datasets of two large clinical cohorts, TCGA (n = 498) and SU2C/PCF (n = 118)." (PMID 31909204, 2020). "The released SOD-Fe0 and Lapa were further endocytosed by tumor cells and the Lapa produces superoxide anion (O2-•) through the catalysis of NQO1 that is overexpressed in tumor cells, while O2-• is converted to H2O2 via SOD." (PMID 32483451, 2020). "β-lapachone (β-lap) is reduced in tumor cells by the enzyme NAD(P)H: quinone acceptor oxidoreductase 1 (NQO1) to a labile hydroquinone which spontaneously reoxidises to β-lap, thereby generating reactive oxygen species (ROS) and oxidative stress." (PMID 32789798, 2020). "When compared to the parental cells, we verified that NQO1 knock-out significantly suppressed the HCC tumor sizes in orthotopically transplanted HCC mice." (PMID 31842909, 2019). "Of note, B16 tumors overexpressing NQO1 grew much faster than B16 parent cells, indicating that NQO1 promotes in vivo tumor growth." (PMID 31324798, 2019). "Treatment with the combination of THC and NQO1 inhibitor resulted in a significant inhibition of PDX tumor growth compared with that after control or monotherapy (inhibition at day 70: NQO1 inhibitor 1.9%, THC 40.7%, THC plus NQO1 inhibitor 72.6%)." (PMID 30737573, 2019). "Taken together, our results strongly suggested an important role of NQO1-induced SIRT6 stability in tumor biology of HCC." (PMID 31842909, 2019). "In sharp contrast, NQO1 overexpressing (clone #1 and #4) tumor-bearing mice showed a dramatic tumor suppression after β-lap treatment." (PMID 31324798, 2019). "A similar effect was observed in NQO1 overexpressing B16 tumor model, suggesting that the adaptive immune system is required for the profound antitumor effect of β-lap in vivo." (PMID 31324798, 2019). "In this study, we showed that NQO1 suppressed tumor characteristics in cutaneous SCC cells, suggesting that NQO1 functions as an antitumorigenic regulator in SCC development and progression." (PMID 31886179, 2019). "While there are many members of the NADPH dehydrogenase family, the expression level of NAD(P)H: quinone oxidoreductase-1 (NQO1) is approximately 12–50 fold higher in tumour cells." (PMID 31137744, 2019). "We used the NQO1-overexpressing B16 tumor model to evaluate the therapeutic efficacy of β-lap and anti-PD-L1 combination treatment." (PMID 31324798, 2019). "To assess the antitumor effects of THC and NQO1 inhibitor in vivo, we evaluated the tumor growth inhibition in ESCC PDX tumors." (PMID 30737573, 2019). "NQO1 is a two-electron oxidoreductase expressed in multiple tumor types at levels 5- to 200- fold above normal tissues, and is a potential therapeutic target." (PMID 31324798, 2019). "In orthotopic mouse model, NQO1 knock-out inhibited tumor growth and induced apoptosis while this effect was effectively rescued by SIRT6 overexpression or MG132 treatment partially." (PMID 31842909, 2019). "NAD(P)H:quinone oxidoreductase 1 (NQO1) is a flavoprotein that is elevated in the tumor tissues in the range of 100-200-fold compared with that of normal tissues." (PMID 31858276, 2019). "Together, these results provide evidence that β-lap selectively suppresses NQO1 positive murine tumor growth in vitro and in vivo; NQO1 is essential and sufficient for β-lap-mediated antitumor effect." (PMID 31324798, 2019).
tumor (continued). "β-Lapachone is catalyzed and bioactivated by NQO1 to generate ROS in NQO1high tumor cells triggering oxidative stress and release of the damage signals for innate sensing." (PMID 31324798, 2019). "MG132 treatment blocked tumor growth inhibition induced by NQO1 knock out, accompanied with increased level of SIRT6 and XIAP." (PMID 31842909, 2019). "Here, we demonstrate that NQO1-targeting prodrug β-lapachone triggers tumor-selective innate sensing leading to T cell-dependent tumor control." (PMID 31324798, 2019). "After 20 patients were analysed, enrolment was restricted to patients with NQO1-high tumours (H-score ≥ 200)." (PMID 30318513, 2018). "NAD(P)H:quinone oxidoreductase 1 (NQO1) is a two-electron oxidoreductase expressed in multiple tumour types." (PMID 30318513, 2018). "In the presence of NQO1 enzyme which is upregulated in several tumours, the benzoquinone gets reduced leading to the opening of the pores and the release of doxorubicin." (PMID 30082647, 2018). "After analysis of the first 20 patients with available efficacy and NQO1 biomarker data, which occurred after accrual of the first 34 patients, enrolment was restricted to those patients with NQO1-positive tumours (defined as H-score ≥ 200)." (PMID 30318513, 2018). "On the other hand, depletion of NQO1 robustly diminishes the cell proliferation, supporting that NQO1 levels are essential for determining proliferation of these tumor cells." (PMID 30595797, 2018). "Based on our preclinical findings and β-lap’s mechanism of action, we included assessment of tumour NQO1 expression by immunohistochemistry (IHC) as an exploratory (and subsequently enrolment) biomarker." (PMID 30318513, 2018). "This study is the first human clinical trial study to suggest an association between β-lap efficacy and positive expression of NQO1 in tumours." (PMID 30318513, 2018). "Previous studies showed that Nrf2 or NQO1 expression was elevated in tumor tissues and correlated with the poor outcomes of patients with gastric cancer." (PMID 28501854, 2017). "In this study, we detected expression of Nrf2 and NQO1 in tumor tissues of NSCLC patients and investigated the roles of these genes as prognostic factors." (PMID 28501854, 2017). "Note that high mRNA expression levels of all three distinct NQO1 probes showed an association with reduced relapse-free survival (RFS, i.e., higher tumor recurrence)." (PMID 28411284, 2017). "Consistently, HIF-1α-knockdown almost completely inhibited tumour growth, even in the presence of overexpressed NQO1." (PMID 27966538, 2016). "NQO1 knockdown tumours displayed dramatically reduced growth rate, whereas tumours overexpressing NQO1 grew much faster as compared with control tumours." (PMID 27966538, 2016). "Probe 1 demonstrated an in vivo tumor growth suppression of 79%, a result highly dependent on the expression of NQO1, as gene knockdown resulted in a significantly attenuated growth inhibition effect (28% growth reduction) in A549 tumor xenografts." (PMID 30034745, 2016). "We have recently identified that Tanshinone IIA (TSA), a natural compound contained in Danshen, elicits its anti-tumor efficacy via targeting NQO1." (PMID 27566573, 2016). "Conversely, NQO1-knockdown tumours (RKO/pshNQO1) showed significantly less HIF-1α expression even in the pimonidazole-positive hypoxic areas." (PMID 27966538, 2016). "In sharp contrast, NQO1 overexpressing tumours showed accelerated growth rate with higher cellular proliferation." (PMID 27966538, 2016). "The results obtained from the tumor xenograft study further support the importance of LAT1-NAD+-SIRT1-FOXO1 pathway in NQO1 substrates induced antitumor effect." (PMID 27566573, 2016). "This suggests that tumour growth is inhibited specifically through reduced NQO1-dependent HIF-1α expression." (PMID 27966538, 2016).
tumor (continued). "To determine the functional contribution of NQO1 to HIF-1α expression and tumour growth in vivo, we evaluated the growth rate of NQO1-knockdown or overexpressing RKO xenografts in female BALB/c nude mice." (PMID 27966538, 2016). "NQO1 catalyzes reactions that have a protective effect against redox cycling, oxidative stress and neoplasia." (PMID 25885439, 2015). "Both positive and strongly positive rates of NQO1 protein expression were significantly higher than both in adjacent non-tumor and normal lung tissues." (PMID 25880877, 2015). "Recently, NQO1 has been targeted in tumor cells, exemplifying an ‘enzyme directed’ approach to anticancer drug development." (PMID 25885439, 2015). "Within the database, 59 directly matched tumor versus normal tissue samples also showed the same elevated NQO1:Catalase ratio (SF1)." (PMID 26602448, 2015). "The analysis showed that there was down-regulation of the p62 and NQO1 signals in the tumor tissues relative to paired NCMT samples." (PMID 25714028, 2015). "To verify the effect of RRx-001 on Nrf2 activation, we assayed the expression of Nrf2 downstream antioxidant enzymes HO-1 and NQO1 in RRx-001 treated cells in vitro and in vivo in tumor-bearing mice." (PMID 26280276, 2015). "Our data strongly suggest that NQO1 bioactivatable drugs enable tumor-selective use of DNA repair inhibitors, such as MeOX." (PMID 26602448, 2015). "Recently, NQO1 has been used as the target enzyme in tumor cells to exemplify the ‘enzyme directed’ approach to anticancer drug development." (PMID 25880877, 2015). "We found that 7 genes (IFITM1, SMAD6, TBX15, CHST4, LRRC4, CCL20, and NQO1) showed significantly different promoter methylation levels between tumor and non-tumor tissue (P value < 0.001) in approximately 80 % of the 78 HCCs." (PMID 26300991, 2015). "The bioactivation property of NQO1 renders it an ideal target for developing anti-tumor drugs, since NQO1 activities are elevated in various human tumors." (PMID 25885439, 2015). "Here we report the RRx-001 mediated nuclear translocation of Nrf2 and the activation of expression of its downstream enzymes HO-1 and NQO1 in tumor cells." (PMID 26280276, 2015). "This study attempted to explore the role of NQO1 in tumor progression and prognostic evaluation of non-small cell lung cancer (NSCLC)." (PMID 25880877, 2015). "We postulate that due to the possibility of induction of the gene in a tumour setting, it will be necessary to specifically investigate NQO1 protein levels in biopsies, in order to estimate potential sensitivity to 17-AAG." (PMID 24886060, 2014). "Further multivariate survival analysis showed that NQO1 expression was one of the independent prognostic factors, along with tumor clinical stage and Her2 status." (PMID 24499631, 2014). "NAD(P)H dehydrogenase, quinone 1 (NQO1) mRNA levels increased in peripheral blood mononuclear cells, and NF-κB and cyclin D1 levels decreased in tumor biopsies." (PMID 24552536, 2014). "NQO1 expressed by the tumor cells activates the quinone-containing alkylating agents which results in the death of the cells that express NQO1." (PMID 25222473, 2014). "Due to the fact that NQO1 is expressed in particularly high levels in tumor cells, these drugs target cancerous cells before becoming toxic to normal cells." (PMID 23577302, 2013). "It was hard to see any obvious NQO1 expression except faint positive signal in scattered cells in adjacent non-tumor tissue (panel a4)." (PMID 23667609, 2013). "The bioactivation property of NQO1 promises it an ideal target for developing anti-tumor drugs, because various human tumors have elevated NQO1 activities." (PMID 22848731, 2012). "In this case, NQO1 is utilized as a tumor selective enzyme to bioactivate the prodrug and thus to realize a tumor specific toxicity." (PMID 22848731, 2012).